MPO (myeloperoxidase)
Diseases named in the same sentence as MPO in open-access papers (continued):
Sharing a sentence is not in itself a finding about the gene and the disease.
cardiovascular disease (continued). "Previous research showed that statins could reduce the MPO levels in patients with cardiovascular diseases." (PMID 27342818, 2016). "Many studies showed that statins, by their anti-inflammatory and antioxidant properties, could reduce the levels of plasma MPO in patients with cardiovascular diseases, and inhibit MPO mRNA expression in macrophages." (PMID 27342818, 2016). "The lack of association was somewhat unexpected and the authors suggested that MPO levels allow the differentiation of the leukocyte-based pathophysiologic contribution to cardiovascular disease from a generalized systemic inflammatory process that was more mirrored with hsCRP." (PMID 26539521, 2015). "Further investigations are needed to clarify detailed mechanisms involved in the reactions between MPO and A1M, and may also reveal a correlation between A1M, MPO and patients with cardiovascular diseases." (PMID 25698971, 2015). "There is evidence that platelet aggregation and MPO concentration in blood plasma increase concomitantly with progression of a cardiovascular disease, and numerous reports reveal the interrelations between platelets and neutrophils in inflammation and thrombosis." (PMID 24143278, 2013). "Our data might indicate that cardiovascular disease is more often present in patients with MPO-ANCA." (PMID 16677376, 2006). "Whether there is a relationship between anti-hHSP60 and cardiovascular disease in patients with MPO-ANCA remains to be studied." (PMID 16677376, 2006). "Thus, MPO seems to be a biomarker for systemic inflammation related to cardiovascular disease." (PMID 39409000, 2024). "Both MPO and LIGHT are associated with increased cardiovascular disease risk and in particular sCD163 is associated with both incidence and death from cardiovascular disease, and thus reduced levels of these could be one of the mechanisms contributing to the cardioprotective effects of liraglutide." (PMID 38685051, 2024). "MPO, a pro-oxidant enzyme, may be a promising target for cardiovascular diseases." (PMID 35983482, 2022). "Thus, MPO is a promoter, mediator and marker of cardiovascular diseases." (PMID 36404308, 2022). "Furthermore, MPO plays a critical role in the modulation of vascular function by limiting the bioavailability of nitric oxide (NO), an important anti-inflammatory and vasodilating agent, thus promoting endothelial dysfunction and cardiovascular disease." (PMID 36670895, 2022). "Whereas myeloperoxidase has a protective role in inflammatory processes, persistent generation of myeloperoxidase-derived oxidants may become deleterious and can also contribute to the development of cardiovascular diseases." (PMID 29991814, 2018). "Statins could reduce the MPO levels in patients with cardiovascular diseases." (PMID 27342818, 2016). "Myeloperoxidase (MPO) is a leukocyte-derived enzyme that links reactive oxygen species to inflammation, making it a potential target for cardiovascular disease." (PMID 40528106, 2025). "MPO effectively reverses the cardioprotective effect of high-density lipoproteins (HDL), which contributes to the development of cardiovascular diseases." (PMID 37513924, 2023). "In this study, we found that MPO is significantly elevated in AAA patients, not only in comparison to the healthy donors, but also compared to PAD patients with cardiovascular disease." (PMID 35203427, 2022). "Among the 10 cardiovascular disease markers tested, 7 showed significant differences between groups (D-dimer, GDF-15, myoglobin, sICAM-1, MPO, P-selectin and lipocalin-2/NGAL)." (PMID 36163447, 2022). "In this sense, it has been suggested that some enzymes, such as myeloperoxidase (MPO), a heme protein derived from leukocytes, play an important role in leukocyte-mediated endothelium damage in inflammation and cardiovascular diseases." (PMID 27007571, 2016). "With this respect, MPO and PAPP-A have been studied for their potential to serve as novel biomarkers for cardiovascular disease." (PMID 21188207, 2010).
cardiovascular disease (continued). "Targeting MPO activity or blocking specific oxidative pathways may help preserve elastin structure and prevent ECM destabilization in cardiovascular diseases." (PMID 41312739, 2025). "In the pathogenesis of T2DM, a ROS flux is an independent factor modulated by MPO, regardless of metformin therapy and concomitant cardiovascular diseases." (PMID 37569455, 2023). "Moreover, MPO is considered as a mutual contributor to the higher incidence of OSA and cardiovascular diseases." (PMID 37569455, 2023). "Newer ones such as galectin-3, lysophosphatidylcholine, copeptin, sST2, S100B, myeloperoxidase and GDF-15 have been extensively studied in recent years as alternatives with an increased sensitivity for cardiovascular diseases, but also with significant results in the field of neurology." (PMID 34821692, 2021). "Notably, in respiratory and cardiovascular disease, SCN− appears to be protective against disease via direct modulation of MPO activity, favouring the production of the HOSCN oxidant." (PMID 32899436, 2020). "Even though myeloperoxidase is an important enzyme related to inflammation, cardiovascular disease, and uric acid oxidation, it is not the only peroxidase present in plasma and is likely not the solely responsible for uric acid oxidation in plasma." (PMID 29924138, 2018). "In conclusion, increased serum myeloperoxidase levels are associated with rapid lung function decline and poor cardiovascular outcomes in COPD patients, which support the emerging role of myeloperoxidase in the pathogenesis of COPD progression and cardiovascular disease." (PMID 23637811, 2013). "Myeloperoxidase (MPO) is a marker of plaque vulnerability and a mechanistic bridge between inflammation and cardiovascular disease, and thus is a suitable target for therapeutic strategy against cardiovascular disease." (PMID 22014237, 2011). "However, monocyte-derived MPO has a relatively low impact on cardiovascular diseases and likely does not play a significant role in the mechanisms under investigation here." (PMID 38736886, 2024). "In summary, MPO inhibition did not affect atherosclerotic lesion size but did promote atherosclerotic plaque remodeling in mice, which is consistent with its known role in humans to promote cardiovascular disease." (PMID 30889221, 2019). "The presence of pro-MPO in patients with cardiovascular disease has not been investigated." (PMID 29590135, 2018). "In summary, we found that serum MPO levels were significantly related to rapid lung function decline and poor cardiovascular outcomes in COPD patients, which is in line with the hypothesis that MPO plays an active role in the pathogenesis of COPD progression and cardiovascular disease." (PMID 23637811, 2013).
inflammation (92 papers, 2006 to 2025). Aberrant reaction of the microcirculation characterized by movement of fluid and leukocytes from the blood into extravascular tissues. "Since acute lung inflammation is believed to be associated with neutrophil infiltration, the infiltration of neutrophil‐like cells that stained positive for MPO+ and Gr‐1+ was characterized." (PMID 38311577, 2024). "Given the significant presence of MPO at sites of inflammation and its role in bystander tissue damage, we sought to examine the molecular mechanisms of MPO action on the development of chronic inflammation and associated MPO-mediated mucosal damage." (PMID 39133648, 2024). "MPO deficient mice had significantly increased numbers of airway infiltrated neutrophils compared to wild-type mice during the whole course of lung inflammation." (PMID 26998194, 2016). "On the other hand, Haegens and coauthors showed reduced inflammation in lungs of MPO deficient mice compared with wild-type mice despite employing a similar model of acute lung inflammation induced by intranasal LPS instillation." (PMID 26998194, 2016). "Intranasal instillation of LPS (0.3 mg/kg) in the wild-type and the MPO deficient mice induced acute airway inflammation, characterized by an increase of the lung lavage cell numbers." (PMID 26998194, 2016). "Thus, normal MPO function is important to intestinal health and its deficiency leads to gut inflammation and dysbiosis." (PMID 41393901, 2025). "Fecal MPO is a marker of neutrophilic inflammation in various inflammatory bowel conditions and is linked to chronic inflammation in EED that may be a driver hindering with vaccine immunogenicity." (PMID 35534310, 2022). "On the other hand, a synthetic FFAR4 agonist GSK 137647 (administered at the dose of 1 mg/kg BW, i.p., twice daily) alleviated DSS-induced intestinal inflammation in mice, as indicated by significantly reduced MPO activity and macroscopic parameters, such as BW loss." (PMID 34833919, 2021). "The employed MPO deficient mice were reported to have total white blood cell counts and differentials similar to the wild-type animals, which was confirmed in our study in both controls and during the course of acute lung inflammation." (PMID 26998194, 2016). "Similarly, in the model of transplantation induced lung inflammation the MPO deficient mice exhibited higher levels of TNF-α and the chemoattractant MCP-1 compared to the wild-type mice." (PMID 26998194, 2016). "The gamma irradiation of antigens can enhance slow release by generating smaller soluble protein aggregates like an adjuvant or oxidizing the antigens, as similarly reported for neutrophil myeloperoxidase in acute inflammation." (PMID 39852865, 2025). "Compared to HFD‐fed WT mice, HFD‐fed Nod1−/− mice exhibited increased lung inflammation, as evidenced by higher neutrophil MPO expression and activity and elevated secretion of the cytokines TNF‐α, IL‐1β, and IL‐6." (PMID 40616268, 2025). "In ABX-treated HTGAP mice, administration of A. mucilyticum exacerbated pancreatic inflammation, as demonstrated by elevated serum lipase levels, increased pancreatic MPO activity, and aggravated histological damage." (PMID 41300441, 2025). "Bhatia and Hegde noted a decrease in pancreatic myeloperoxidase (MPO) and macrophage inflammatory protein-2 (MIP-2) associated with acute pancreatic inflammation." (PMID 39634607, 2024). "MPO is one of the main toxic mediators from neutrophils and leads to tissue disruption during pulmonary inflammation." (PMID 38230250, 2024). "Oral administration of esculin at doses of 5, 10, and 25 mg/Kg with TNBS-induced intestinal inflammation in rats alleviated the symptoms of gut damage, reducing MPO activity and counteracting GSH depletion when treated with 25 mg/Kg." (PMID 37111267, 2023). "MPO activity has been shown to be directly relative to the neutrophil number in animal models of intestinal inflammation." (PMID 37895046, 2023).
inflammation (continued). "Reduction of damage score and MPO activity was also demonstrated after the intrarectal administration of esculetin at 100 and 200 μM in rats with intestinal inflammation previously induced by TNBS." (PMID 33467396, 2021). "There is evidence to suggest that IL-8 and myeloperoxidase (MPO) are biomarkers in the CF sputum at different stages of lung inflammation, such that IL-8 correlates with exacerbations, and MPO and IgG degradation correlates with lower FEV1% score." (PMID 34200034, 2021). "Sinomenine can alleviate LPS-induced lung inflammation by inhibiting the expression of nitric oxide (NO), myeloperoxidase (MPO), TNF-α, and IL-6." (PMID 32256634, 2020). "The present study found that compared with the control group MPO expression was elevated in DSS-induced acute intestinal inflammation mice." (PMID 31262973, 2019). "In this study, we performed immunofluorescent staining of MPO in the pancreatic tissues, which was used to reflect the degree of pancreatic inflammation." (PMID 29849486, 2018). "Using this method, we demonstrated that ectopic expression of C/A MYPT1 reduces lung inflammation (MPO staining) and attenuates LPS-induced vascular permeability (Evans Blue Dye albumin (EBA) extravasation into the lung)." (PMID 27976727, 2016). "Intestinal inflammation was verified through histological evaluation and myeloperoxidase (MPO) activity." (PMID 24414342, 2015). "The treatment with LLLT reduced the development of neutrophilic lung inflammation induced by FA, as observed by the reduced number of leukocytes, mast cells degranulated, and a decreased myeloperoxidase activity in the lung." (PMID 26569396, 2015). "Acute pulmonary inflammation was assessed by histology, pulmonary myeloperoxidase (MPO) activity, and pulmonary IL-6 concentration." (PMID 24886543, 2014). "Acute pulmonary inflammation was assessed by pulmonary myeloperoxidase (MPO) activity and pulmonary H&E histopathology." (PMID 22046081, 2012). "Similarly, a study in rural Odisha found an inverse association between MPO levels and height-for-age z-scores (HAZ), confirming that gut inflammation is strongly linked to stunting." (PMID 41416291, 2025). "Furthermore, MPO-knock-out mice subjected to 5/6 nephrectomy displayed lower renal damage (albuminuria, glomerular injury, and renal inflammation) and lower plasma MPO levels than WT mice." (PMID 39861371, 2025). "Additionally, statins reduce Myeloperoxidase (MPO) activity, decrease oxidative stress and vascular inflammation, and improve endothelial function by enhancing nitric oxide bioavailability, which reduces endothelial activation and inflammation." (PMID 41511355, 2025). "Harmane combats inflammation by inhibiting myeloperoxidase (MPO), a pro-inflammatory enzyme which plays a crucial role in the innate immune response and stands as a crucial marker for diseases associated with chronic inflammation." (PMID 39201652, 2024). "Investigation of the protective effects of curcumin on ALI models has shown that curcumin reduced histopathological injury, lung inflammation, and myeloperoxidase (MPO) activity, which is used to measure neutrophil presence and as an indirect lung injury indicator." (PMID 36677800, 2023). "Similarly, MPO inhibition improves colonic wound healing, indicating an important detrimental role of MPO in colon inflammation." (PMID 36293108, 2022). "However, to understand the role of CD16+ monocytes in renal inflammation in MPO-AAV, further studies are required." (PMID 36059489, 2022). "It has been reported that carbon nanotube or asbestos exposed MPO deficient mice has a milder lung inflammation in the acute phase than WT mice as well, suggesting that MPO were involved in the process of pulmonary inflammation by nanomaterials and accelerated the inflammation." (PMID 30352603, 2018).
inflammation (continued). "The positive areas of MPO staining were mainly neutrophils and macrophages that phagocytosed neutrophils at inflammatory lesions such as the granulomatous area at 1 month in the NiO-, CeO2- and MWCNT (L)- high exposure groups, also suggesting that MPO is involved in lung inflammation." (PMID 30352603, 2018). "MPO activity in H-HO1t, H-HO2t and H-HO3t groups was markedly lower than in control groups, which is associated with HO-1-induced reduction in intestinal stress (decrease in PMN activation and inhibition of intestinal inflammation)." (PMID 28591377, 2017). "In this study, the importance of MPO in the course of acute lung inflammation was evaluated." (PMID 26998194, 2016). "Understanding the role of S100A12 and MPO in the pathogenesis of chronic intestinal inflammation in future may result in an improved understanding of canine chronic intestinal inflammation." (PMID 26370713, 2015). "Intestinal inflammation was verified through histological evaluation and myeloperoxidase activity." (PMID 24414342, 2015). "SIRS was assessed by serum proinflammatory cytokines (TNF-α, IL-1β, CXCL1, IL-6), ALI was assessed by lung inflammation (lung myeloperoxidase [MPO] activity), and AKI was assessed by serum creatinine, BUN, and glomerular filtration rate (GFR) (by FITC-labeled inulin clearance) at 4 hours." (PMID 24265742, 2013). "In fact, lung MPO activity is regarded as one of the most sensitive markers of lung inflammation available, thus we believe lung MPO activity is a suitable marker of lung inflammation and, at the very least, the initiation of lung injury post endotoxin injection and post CLP." (PMID 24265742, 2013). "Pancreatic inflammation was assessed by measuring pancreatic MPO activity and histology." (PMID 22396778, 2012). "Histologic techniques were used to assess pulmonary inflammation, characterize the adherence of leukocytes to systemic venules, verify the presence of myeloperoxidase (MPO) in the systemic microvascular wall, and quantify systemic microvascular oxidative stress." (PMID 16507465, 2006). "The important finding in this study was the correlation between plasma MPO and IL-17 levels in all study participants (R2 = 0.9110, P < 0.05), supporting the hypothesis that IL-17, as MPO, is a powerful indicator of acute coronary inflammation." (PMID 25045198, 2014). "Circulating markers such as IL-6, myeloperoxidase (MPO), MMP-9, hsCRP, CD47, and LDL cholesterol have demonstrated utility in characterizing chronic vascular inflammation." (PMID 41007845, 2025). "In the same experimental model of intestinal inflammation using C57BL/6 female mice, esculetin orally administered at 20 mg/Kg ameliorated intestinal injury, decreased MPO activity and IL-6 and TNF-α production, and inhibited NF-κB/MPAKs signaling pathways." (PMID 37111267, 2023). "Lung inflammation was evaluated by total cell and neutrophil counts in BALF, MPO, and cytokines and chemokines in BALF and pulmonary tissues." (PMID 37626408, 2023). "Mice depleted of Tregs showed enhanced accumulation of neutrophils in the lungs and an increase in MPO levels in the BALF, confirming the suppressive role of Tregs during Be-induced lung inflammation." (PMID 35819849, 2022). "Our results shown that PE effectively alleviate mammary inflammation by inhibiting the expression and secretion of IL-6, IL-1β, TNF-α in vivo and in vitro, and inhibiting the synthesis of iNOS and MPO." (PMID 34383710, 2021). "CEACAM1 correlated with vascular inflammation in the aorta, and CEACAM1, MMP9, MPO, ERV3-1, UBALD2 and LSMEM1 correlated with vascular inflammation in the carotid arteries." (PMID 34639156, 2021). "In the carrageenan-induced paw inflammation model, both LEA and HEA reduced MPO activity in the subcutaneous tissues of the paw." (PMID 35095910, 2021). "Intestinal inflammation is a key feature of EED, and several fecal markers—MPO, NEO, and calprotectin—indicate intestinal inflammation." (PMID 29351288, 2018).
inflammation (continued). "MPO activity is a marker of PMN neutrophil, whereas iNOS increases NO production and mediates lung inflammation." (PMID 22454687, 2012). "In control mice, ozone exposure induced lung inflammation as evidence by increased leukocyte count, protein concentration in BAL and myeloperoxidase activity, pro-inflammatory cytokine levels in LH." (PMID 21595935, 2011). "All these data indicated that AEE could prevent lung inflammation during ALI in rats by decreasing CRP, MPO, and MIF in a dose-dependent manner." (PMID 35967416, 2022). "Similarly, the colonic myeloperoxidase (MPO) activity, a biochemical assay for acute intestinal inflammation, was significantly alleviated by the anti-IL23P19 treatment." (PMID 27029486, 2016). "Our data show that neutrophils adhere to the cerebrovasculature in a mouse model of LPS-induced systemic inflammation and release/deposit MPO that does not colocalize with neutrophils." (PMID 23691142, 2013). "In conclusion, these results suggest that neutrophil-derived MPO may play an important role in regulating the course of pulmonary inflammation, independent of its putative microbicidal functions." (PMID 26998194, 2016).